CD33 (CD33 molecule)
Diseases named in the same sentence as CD33 in open-access papers (continued):
Sharing a sentence is not in itself a finding about the gene and the disease.
tumor (continued). "Myeloid-derived suppressor cells are important for immunosuppression, and their surrogate biomarker, CD33, is related to aggressive tumor phenotypes and short survival durations." (PMID 40551711, 2025). "By targeting tumor-associated antigens, such as CD33 or EGFR, while simultaneously inhibiting checkpoint pathways like PD-1/PD-L1 or CTLA-4, CiTEs overcome immune suppression within the tumor microenvironment and restore T-cell activation." (PMID 39982231, 2025). "In contrast, very few graft cells were detected in mice from the CD33(+)CD16b(-) cohort, suggesting high selective killing in vivo of tumor vs. surrogate normal cells." (PMID 40191207, 2025). "A representative example is BMS-986497 (formerly ORM-6151) which utilizes an anti-CD33 antibody to deliver a GSPT1-targeting PROTAC into CD33-positive tumor cells." (PMID 40507351, 2025). "Hematological toxicity was another common side effect of GO, presumably driven by on-target off-tumor activity of targeting CD33 on normal myeloid cells, which has been observed with other CD33-targeted therapeutics." (PMID 41249828, 2025). "We defined selectivity as a ratio of ET50 using surrogate normal CD33(+)CD16b(+) cells divided by ET50 using tumor CD33(+)CD16b(-) cells." (PMID 40191207, 2025). "CD33 and CD45-positive cells were isolated from the bone marrow and spleen when animals approached the endpoint, and aITGB2 expression in the CD33/CD45-positive tumor population was analyzed using flow cytometry." (PMID 41282197, 2025). "For these studies we utilized an M2T-CD33 construct using the mouse CD33 ECD (AAs 18-240, M2T-mCD33) to identify off-tumor adverse effects of mounting an immune response against CD33 in rodents." (PMID 41249828, 2025). "Their accumulation in the tumor mass correlates with high oncogenic cell cycle-related kinase (CCRK)/IL-6/CD11b/CD33 expression and poor prognosis." (PMID 40136652, 2025). "In a diet-induced obesity model, CD33+ myeloid-derived suppressor cells (MDSCs) are increased within the tumor microenvironment, which contribute to tumor-promoting immunosuppression." (PMID 41301440, 2025). "For instance, Thorium-227 (227Th)-labeled CD33 antibodies have exhibited potent anti-tumor effects in HL-60 xenograft mouse models." (PMID 40227793, 2025). "Compared to their first-generation counterparts, second-generation CD33 TriKEs demonstrated superior NK cell activation, expansion, and tumor control in vitro and in vivo." (PMID 40474230, 2025). "In clinical settings, both MO-MDSC (CD33+CD14+CD15–HLA-DRlo) and PMN-MDSC (CD33+CD14–CD15+HLA-DR–) had pro-tumor effects, and the ratio of these two subsets was distinct among different tumor types and therefore potentially impacted treatment strategies." (PMID 41360769, 2025). "By day 41, all mice treated with [225Ac]DOTA-anti-CD33 showed high tumor burden and reached endpoint." (PMID 41282197, 2025). "An eleven-marker panel (CD3, CD4, CD8, FOXP3, CD68, arginase-1, CD33, HLA-DR, pan-keratin (PanCK), PD-1, and PD-L1) was used to study the tumor and immune cell compositions." (PMID 38898200, 2024). "Results from heterodimeric T-BsAbs bearing a Fab with an irrelevant specificity (CD33) indicated that tumor bivalency was required for meaningful tumor control in vivo." (PMID 38650005, 2024). "CD33 CAR-NK anti-tumor cytotoxicity was tested in vitro with tumor cell lines and primary samples obtained from AML patients, and showed enhanced cytotoxicity and cytokine secretion compared to non-modified NK cells." (PMID 38694825, 2024). "When cocultured with CD33+ HL-60 tumor cells, CAR33 T cells had robust IFN-γ production in the presence or absence of rapamycin, while DARIC33 only secreted cytokines in the presence of rapamycin." (PMID 38502193, 2024). "Research has focused on the CD33 antigen as a therapeutic target because most AML tumor cells express this marker on their surface, whereas normal hematopoietic stem cells do not." (PMID 38255313, 2024).
tumor (continued). "We next evaluated the in vivo tumor-residence time of both adaptors by injecting tumor-bearing mice with CD33 or CD117 Db-FM." (PMID 39294295, 2024). "We found that the number of CAR T cells and tumor cells in NSG mice of CD33 CARKR group was higher than the CD33 CAR group." (PMID 38184596, 2024). "It was confirmed that in the immunodeficient mouse model where CD16/IL-15/CD33 TriKE induced maintain and survival of NK cells and exhibited superior anti-tumor effect." (PMID 38396050, 2024). "For example, we can see SIGLEC-9,7, and CD33 remain the strongest correlations with the others in both the normal sample and the tumor sample, while SIGLEC10’s correlation experienced a strong boost after getting COAD." (PMID 38650859, 2024). "Hematologic tumor antigens included CD33 (3 out of 33 studies), CD123 (3 out of 33 studies), CD20 (5 out of 33 studies), and CD19 (3 out of 33 studies)." (PMID 39712013, 2024). "Compared to low tumor CD33+ cell infiltration, high tumor CD33+ cell infiltration was associated with worse OS (p = 0.018)." (PMID 38841570, 2024). "These antigens, such as CD123 and CD33, are present on tumor blast membranes and have the greatest clinical relevance." (PMID 38400148, 2024). "Homodimeric EGFRxEGFR and HER2xHER2 T-BsAbs were heterodimerized with a CD33-specific control T-BsAb, generating EGFRxCD33 and HER2xCD33 T-BsAbs bearing one tumor-targeting Fab and one non-tumor-targeting CD33 control Fab." (PMID 38650005, 2024). "The increased presence of myeloid-derived suppressor cells (MDSCs), in metastatic UVM, as identified by CD11b, CD14, and CD33, underscores their potential role in facilitating tumor progression and immune evasion." (PMID 39916959, 2024). "Next, we evaluated the anti-tumor activity of CD33 CAR T cells in NSG mice that were pre-inoculated with either U937CD33 or Nalm6CD33 cells." (PMID 39039086, 2024). "Following coculture with CD33+ tumor cells, both CAR33 and DARIC33 T cells exhibited a similar activation profile; however, the CAR33 cells had higher expression of PD-1, LAG3, CD69, and CD25, suggesting greater activation following T cell activation." (PMID 38502193, 2024). "The tumor-infiltrated CD33+ MDSCs increased tumor cell migration, invasion, EMT, and vasculogenic mimicry in in vitro co-culture models." (PMID 38468824, 2024). "At early time points after seeding (4, 8, 12 h), we observed significantly increased ablation of tumor cells expressing both CD33 and CD117 compared to only single-antigen-positive cells." (PMID 39294295, 2024). "EGFR and HER2 T-BsAbs were also heterodimerized with a CD33 control T-BsAb to generate ‘tumor-monovalent’ EGFRxCD33 and HER2xCD33 T-BsAbs." (PMID 38650005, 2024). "In AML, bi-cistronic CAR T, in which a single vector was transduced to produce Bi-CAR-T targeting CD123 and CD33, showed significant anti-tumor activity in cell lines and in vivo." (PMID 39770471, 2024). "Conversely, CD33 Db-FM presented a relatively lower density on the tumor cell surface (1 nM) and experienced a 4.5-fold reduction in surface labeling over the same time, possibly explained by receptor-mediated internalization of CD33 Db-FM." (PMID 39294295, 2024). "Five clusters of PanCK positive tumor cells were identified: PanCK positive, PanCK/PD-L1 double positive, PanCK/PD-L1/CD33 triple positive, PanCK/CD33/FOXP3 triple positive, and PanCK/CD68/CD33/PD-L1/FOXP3 positive." (PMID 38898200, 2024). "Current NK cell engagers are mainly designed with CD16 and tumor epitopes like CD33 simultaneously, which have several additional advantages compared to mAbs." (PMID 38396050, 2024). "To further corroborate our findings, we used cancer patient-derived CD33+ cells from primary tumor homogenates together with autologous CD8+ T cells isolated from PBMCs." (PMID 38448555, 2024).
tumor (continued). "The GTB‐3550 TriKE (CD16/IL‐15/CD33), showing promising anti‐tumour efficacy in early studies, led to the launch of a phase I/II clinical trial for treating refractory AML and high‐risk MDS." (PMID 39472273, 2024). "The type and spatial distribution of the immune infiltrate in EOC was assessed by IHC upon staining for CD3, CD20 and CD163 on the whole cohort, and by flow cytometry by CD3, CD19 and CD33 on 19 freshly processed tumor samples." (PMID 37868997, 2023). "Results show that C3AR1 has the strongest correlation with M2 macrophages (CD163, MRC1, CD209), tumor-associated macrophages (CCL2, CD86, CD68) and monocyte immune markers, including (CD14, CD33, ITGAX)." (PMID 37005667, 2023). "What is more, the clinical safety and anti-tumor activity of CD33-CAR NK-92 has been tested in relapsed and refractory AML patients." (PMID 37112766, 2023). "The anti-HLA-DR iCAR was co-expressed with anti-CD19 or anti-CD33 activating CARs and mediated highly selective killing of HLA-DR-negative tumor cells in vitro and in a xenograft mouse model." (PMID 36922828, 2023). "Analyses of tumor-infiltrating huCD45+ immune cells confirmed reduction of human MDSC (HLA-DR-CD11b+CD33+), together with increased infiltration of CD8+ T cells." (PMID 37542037, 2023). "CD33 deletion in primary HSPCs maintained their full function in terms of engraftment and differentiation, and it efficiently reduced off-tumor targeting while preserving on-tumor efficacy." (PMID 37345050, 2023). "Tumour tissue from multiple different cancers express TGF-β and this expression is closely associated with infiltration of CD14+CD33+ myeloid cells." (PMID 37033972, 2023). "In one of the first efforts, CAR‐T‐cell therapy targeting CD33 was performed in a patient with relapsed or refractory AML and reported that the tumor burden of this patient was significantly decreased in the bone marrow after anti‐CD33 CAR‐T‐cell therapy." (PMID 36583504, 2023). "NSG-SGM3 mice (male, 9–13 weeks old) received 0.5 × 106 OCI-AML2 cells (GFP+, Luciferase (Luc)+) intravenously followed by a single administration of 1 × 107 CD33-CAR-NK cells at day 3 post tumor cell injection." (PMID 35418180, 2022). "For example, the timing of an anti-CD33 antibody uptake, retention and washout from the tumor will determine the timing of administration of an additional anti-cancer agent(s) for combination therapy to achieve a synergistic effect." (PMID 36235126, 2022). "CD33 is pathologically overexpressed on MDSCs in blood and tumor tissues from cancer patients to promote tumor growth." (PMID 36131911, 2022). "In recent years, several tumor antigens, such as CD33, CD123, CLL-1, CD70, and TIM-3, have been explored as potential target antigens for AML treatment." (PMID 35267549, 2022). "After binding of the ADC conjugate to tumor cells expressing the CD33 antigen, internalization of the ADC-CD33 complex follows, leading to the formed and intracellular release of N-Calich-DMH by the hydrolytic degradation of the linker." (PMID 35011701, 2022). "In the current study, we labeled lintuzumab with 89Zr and performed in vitro and in vivo characterization of this molecule with the ultimate goal to develop a preclinical tool to study CD33 tumor targeting in AML models using PET." (PMID 36235126, 2022). "Anti-CD33 CARs have proven to be highly effective, even at very low effector to target (E:T) ratios with robust killing of both primary tumors and tumor cell lines at E:T ratios as low as <1 effector cell per 20 targets." (PMID 35267549, 2022). "Several CD16A–BiKEs have been developed to target different tumor antigens, including the epithelial cell adhesion molecule (EpCAM), CD33, CD19, or CD20." (PMID 36231109, 2022). "The radioconjugate cleared from the blood and other organs except for the tumor after Day 1 and accumulated in CD33-positive tumors." (PMID 36235126, 2022).
tumor (continued). "Preclinical investigations have evaluated and validated the tumor-killing efficacy of a CD16/CD33 BiKE against MDS as well as AFM13, a CD16/CD30 BiKE against CD30+ lymphomas." (PMID 36613644, 2022). "Anti-CD33 CAR-T cells were tested in an in vivo prevention model where it showed striking results with the prevention of tumor growth in established AML." (PMID 35267549, 2022). "Conversely, we observed that the MDSCs (labeled by CD11b+CD33+) was obviously recruited in tumor regions with low TMEM170B expression level." (PMID 35601487, 2022). "The binding of anti-CD33 immunoconjugates to CD33 on the tumor cell surface results in the internalization of the antibody drug conjugates (ADCs)-CD33 complex into the cytoplasm and in delivery of the cytotoxic payload." (PMID 35886899, 2022). "To date, anti-AML CAR T cells have shown limited efficacy in the clinic, with on-target off-tumor toxicity being especially problematic in the context of targeting CD33." (PMID 33414484, 2021). "Mice treated with CD33/CD3 nanoTCEs had significantly lower tumor burden at all time points compared with Isotype/CD3 nanoTCEs (excluding Day 6)." (PMID 34548905, 2021). "The correlation between CD68 and CD163 expression was significant and strong in tumor nests (r = 0.764) and moderate in the stroma (r = 0.455) CD33 expression showed significant correlation only with CD163 (r = 0.651 in stroma and r = 0.605 in tumor nests)." (PMID 34200100, 2021). "Gemtuzumab ozogamicin (GO) is one such treatment where calicheamicin is conjugated to an anti-CD33 antibody and has potent anti-tumor effects on CD33-expressing cells, found in a majority of AML cases." (PMID 33439382, 2021). "Next, we investigated genes and their associated pathways, which were steadily upregulated or downregulated in tumor-infiltrating CD33+ myeloid cells of CRC patients across disease stages (Stages I, II and IV)." (PMID 33000418, 2021). "As with PD-L1 expression, a positive correlation with CD3+ TILs was detected for both stromal CD33+ cells (r = 0.292, p = 0.0096) and CD33+ tumor cells (r = 0.327, p = 0.003)." (PMID 33625532, 2021). "As an example, an anti-CD33 mAb called gemtuzumab was fused to an anti-tumor antibiotic, calicheamicin; a complex comprised of gemtuzumab and calicheamicin, the conjugate, was called gemtuzumab ozogamicin." (PMID 34412685, 2021). "225Ac‐lintuzumab delivers the 225Ac payload, a high energy, short path length, alpha emitting radionuclide directly to CD33‐positive myeloid tumor cells creating lethal double‐strand breaks in DNA and leading to selective tumor cell killing." (PMID 33347715, 2021). "This culminates to CAR T-cells eradicating CD33-bearing tumor cells, while CD33-null HSCs proceed to repopulate the BM." (PMID 34446084, 2021). "We constructed BiFabCD20/CD3 and BiFabHer2/CD33 via sortase A-mediated bio-click chemistry and demonstrated their anti-tumor activity through engaging human immune cells." (PMID 34572769, 2021). "A visible number of tumor-associated myeloid cells including CD68+ and CD163+ macrophages and CD33+ myeloid cells were also detected in most tumor tissues." (PMID 34257571, 2021). "Simultaneously, the other is directed against the tumor antigen such as CD33, thereby engaging endogenous T cells with CD33+ AML blast for T-cell-mediated killing." (PMID 34069204, 2021). "A positive correlation was also noted between stromal CD33+ cells and FN+ tumor cells (r = 0.305, p = 0.007)." (PMID 33625532, 2021). "The addition of LV increased the viable population of activated CAR T cells (70% vs 12% viable, 10 μM MTX ± LV) and the CD33-expressing tumor cell line MV4-11 (65% vs 11% viable, 10 μM MTX ± LV)." (PMID 33514714, 2021). "In this study, a visible number of TAMs and CD33-positive myeloid cells were observed in most tumor tissues." (PMID 34257571, 2021).
tumor (continued). "Higher tumor staging showed a trend of higher density of CD33, which suggests that CD33-positive myeloid cells such as MDSCs also play a part in promoting the development of fibroblastic sarcoma." (PMID 34257571, 2021). "One scFv domain is designed to identify an epitope on CD3 and the other is designed to bind a tumor-associated antigen (TAA) expressed by tumor cells (e.g., CD33 in the case of AML)." (PMID 34203180, 2021). "Some in vivo and in vitro studies have shown the sustained substantial anti-tumor activity of CD33-CAR T cell against AML cells, significant tumor eradication, and maintenance of T cell persistence during the cytotoxicity." (PMID 34412685, 2021). "The densities of CD8+ T cells, CD33+ cells (marker for myeloid‐derived suppressor cells [MDSCs]), and CD163+ cells (marker for tumor‐associated macrophages [TAMs]) in CRLM tissue were determined by immunohistochemical staining." (PMID 34464993, 2021). "We have previously reported that CD33+ MDSCs were recruited to peritoneal metastatic lesions via platelet aggregation, which contributed to tumor progression." (PMID 33793095, 2021). "As a consequence, CD33-CAR T cells displayed notable cytolytic functions against CD33+ blasts such as remarkable tumor degradation in the early stage as well as high maintenance of CAR T cell number and cytotoxicity." (PMID 34412685, 2021). "Stromal CD33+ cells significantly correlated with fibronectin in the tumor stroma (r = 0.457, p < 0.0001)." (PMID 33625532, 2021). "We found 1,306 differentially expressed genes (DEGs) between tumor-infiltrating CD33+ cells in CRC patients with early and advanced stages (Log2 FC ≥ 2 and P value cutoff ≤ 0.05)." (PMID 33000418, 2021). "Well-differentiated adenocarcinomas were also characterized by significantly higher coexpression of the CD33 antigen in the tumor stroma." (PMID 33625532, 2021). "MDSCs, usually labeled in combination with CD33+ and other markers, are another important group of tumor-related myeloid cells that accumulate in tumor tissues, promote tumor progression and suppress anti-tumor immune responses." (PMID 34257571, 2021). "We found that CD33+CD11b+HLA-DR− MDSCs and tumour-derived MDSCs were decreased when METTL3 was knocked down in CD33+ cells or HeLa cells." (PMID 33059689, 2020). "Both CD33-specific nanoCARs induced similar T cell activation, cytokine production and tumor cell lysis when incubated with CD33+ cells." (PMID 32019116, 2020). "In the present study, we detected the levels of METTL3 and CD33+ MDSCs in tumour specimens from 197 CC patients by immunohistochemical (IHC) staining." (PMID 33059689, 2020). "CD33-deficient human HSPCs resistant to CD33-targeted therapy mitigate CART33 toxicity to sustain myelopoiesis and to prevent on-target off-tumor toxicity." (PMID 33117361, 2020). "CD123-directed and CD33-directed CAR T cells have both shown highly potent anti-tumor activity in pre-clinical models." (PMID 32435621, 2020). "CD33-positive cells are usually defined as myeloid-derived suppressor cells (MDSCs) with suppressive influence on human tumour tissues." (PMID 33059689, 2020). "Among the anti-CD33 Nbs, Nb_7 showed the highest tumor uptake (2.53 ± 0.69 % injected activity per gram (IA/g), with low background signal, except in the kidneys and bladder." (PMID 31906437, 2020). "Micro-single photon emission computed tomography/X-ray computed tomography (SPECT/CT) images of mice showed fast tumor targeting of anti-CD33 Nbs, with high accumulation of radioactivity in kidneys and bladder for all 99mTc-labeled Nbs." (PMID 31906437, 2020). "In the present study, the levels of METTL3 and CD33+ MDSCs were examined in tumour specimens from 197 patients with CC by IHC." (PMID 33059689, 2020). "Further, tumours with elevated numbers of CD33+S100a9+ cells were generally higher-grade tumours and poorly differentiated with detectable satellite lesions." (PMID 32747748, 2020).